RN7SL380P (RNA, 7SL, cytoplasmic 380, pseudogene)
Gene: Miscellaneous RNA gene on chromosome 12 (6,783,854 to 6,784,161, reverse strand). Ensembl gene ENSG00000244532.
Homologues: Orthologues: chimpanzee Metazoa_SRP (93% identical), macaque Metazoa_SRP (87% identical). Paralogues in human: RN7SL1 (81% identical), RN7SL2 (81% identical), RN7SL3 (81% identical), RN7SL7P (78% identical), RN7SL126P (77% identical), RN7SL45P (77% identical), RN7SL49P (77% identical), RN7SL230P (76% identical), RN7SL652P (76% identical), RN7SL712P (76% identical), RN7SL665P (76% identical), RN7SL448P (75% identical), and 700 more.